ADAM9 (ADAM metallopeptidase domain 9)
Description:
Metalloprotease that cleaves and releases a number of molecules with important roles in tumorigenesis and angiogenesis, such as TEK, KDR, EPHB4, CD40, VCAM1 and CDH5. May mediate cell-cell, cell-matrix interactions and regulate the motility of cells via interactions with integrins. [Isoform 2]: May act as alpha-secretase for amyloid precursor protein (APP).
Synonyms: KIAA0021; MCMP; MDC9; MLTNG; CORD9
Tractability: Small molecule: it belongs to a druggable protein family. Antibody: UniProt places it where antibodies can reach, with high confidence; UniProt predicts a signal peptide or a membrane-spanning region; its Gene Ontology location is reachable by antibodies, with medium confidence. PROTAC: ubiquitination databases record sites on it; its protein half-life has been measured; a small molecule that binds it is known.
Target class: Metallo protease MAM clan; Metallo protease; Protease; Enzyme; Metallo protease M12B subfamily
Gene: Protein-coding gene on chromosome 8 (38,996,754 to 39,105,445, forward strand). Ensembl gene ENSG00000168615.
Subcellular location: Cell membrane (Isoform 1); Secreted (Isoform 2)
Subcellular location (Human Protein Atlas): Vesicles; Endoplasmic reticulum; Predicted to be secreted
Pathways (Reactome):
Extracellular matrix organization: Collagen degradation
Gene Ontology:
Molecular function: collagen binding; integrin binding; laminin binding; metalloendopeptidase activity; metallopeptidase activity; protein binding; SH3 domain binding; protein kinase C binding
Biological process: cell adhesion; cell adhesion mediated by integrin; cell-cell adhesion mediated by integrin; cell-matrix adhesion; cellular response to lipopolysaccharide; keratinocyte differentiation; membrane protein ectodomain proteolysis; membrane protein intracellular domain proteolysis; monocyte activation; positive regulation of cell adhesion mediated by integrin; positive regulation of cell migration; positive regulation of keratinocyte migration; positive regulation of macrophage fusion; positive regulation of MAPK cascade; positive regulation of protein secretion; response to calcium ion; response to hydrogen peroxide; response to manganese ion; response to tumor necrosis factor; transforming growth factor beta receptor signaling pathway; cell migration; integrin-mediated signaling pathway; positive regulation of membrane protein ectodomain proteolysis; response to glucocorticoid; proteolysis
Cellular component: extracellular exosome; extracellular region; focal adhesion; plasma membrane; cell surface; external side of plasma membrane
Genetic constraint (gnomAD): Loss-of-function variants: 47 observed, 104.28 expected, observed/expected ratio (o/e) 0.45, 90% interval 0.36 to 0.57. The upper end of that interval is the gene's LOEUF score, 0.57, which puts it in group 2 of 6, group 1 being the genes least tolerant of losing a copy. Missense variants: 819 observed, 1,022.6 expected, observed/expected ratio (o/e) 0.8, 90% interval 0.75 to 0.85. Synonymous variants: 311 observed, 345.71 expected, observed/expected ratio (o/e) 0.9, 90% interval 0.82 to 0.99.
Homologues: Orthologues: chimpanzee ADAM9 (99% identical), macaque ADAM9 (93% identical), dog ADAM9 (93% identical), rabbit ADAM9 (92% identical), pig ADAM9 (91% identical), guinea pig ADAM9 (87% identical), mouse Adam9 (86% identical), rat Adam9 (82% identical), tropical clawed frog adam9 (66% identical), zebrafish adam9a (60% identical). Paralogues in human: ADAM19 (35% identical), ADAM12 (35% identical), ADAM30 (32% identical), ADAM20 (32% identical), ADAM21 (32% identical), ADAM15 (32% identical), ADAM29 (31% identical), ADAM33 (30% identical), ADAM18 (30% identical), ADAM2 (30% identical), ADAM8 (30% identical), ADAM32 (29% identical), and 8 more.
Diseases named in the same sentence as ADAM9 in open-access papers:
ADAM9 is named in the same sentence as 130 diseases in open-access papers, as found by Europe PMC text mining. Sharing a sentence is not in itself a finding about the gene and the disease. The quoted sentences say what the papers report.
lung carcinoma (35 papers, 2008 to 2025). "Studies have shown a correlation between pneumonia and the development of EGFR mutations in lung cancer, while ADAM9 has been identified as a key player in lung acute or chronic inflammation." (PMID 40429751, 2025). "Several genes are reported to be associated with lung cancer metastasis, such as ADAM9 (a disintegrin and metalloprotease 9) and CDCP1 (CUB-domain-containing protein 1)." (PMID 26553452, 2015). "Additionally, elevated ADAM9 expression was linked to poor OS in lung cancer patients." (PMID 40429751, 2025). "Since tPA has the ability to disrupt the integrity of the BBB by a plasmin-dependent or plasmin-independent pathway, the ability of ADAM9 to enhance the function of tPA may explain why high ADAM9 expression in lung cancer cells is associated with brain metastasis." (PMID 29118335, 2017). "Moreover, ADAM9 deficiency in lung cancer cells reduces metastasis in the brain." (PMID 28260841, 2017). "The expression level of miRNA-1 was reduced in primary lung cancer cells but upregulated in lung cancer cells with ADAM9 gene knockout." (PMID 41416095, 2025). "As a member of the ADAM family, ADAM9 is involved in the occurrence, progression, invasion, metastasis, and prognosis of liver cancer, breast cancer, lung cancer, stomach cancer, kidney cancer, prostate cancer, and other malignant tumors." (PMID 39441449, 2024). "Although ADAM9 has been shown to enhance pulmonary vascular remodeling in lung cancer via VEGFA, angiopoietin-2, and tissue plasminogen activator, there is a paucity of literature linking ADAM9 to PH." (PMID 36522710, 2022). "ADAM9 regulates the expression of angiogenic factor Ang2, thereby controlling vascular remodeling and angiogenesis to regulate lung cancer brain metastasis." (PMID 35874764, 2022). "ADAM9 is known to increase vascular endothelial growth factor A (VEGFA) expression in lung cancer metastasis." (PMID 36404352, 2022). "A lung cancer study reported that the correlation between N-cadherin and ADAM9 was stronger in highly malignant cancers." (PMID 35740916, 2022). "Increased ADAM9 expression has been reported in various cancers, such as hepatocellular carcinoma, prostate cancer, breast cancer, non‐small cell lung cancer, skin melanoma and glioma." (PMID 33811456, 2022). "Micro-RNAs (miRNAs), such as miR-425, miR-488 and miR-590, have been reported as regulators of ADAM9 in lung cancer." (PMID 33096780, 2020). "By immunohistochemical staining, high protein expression of ADAM9 was found to be correlated with a poor 5-year survival rate in an Asian cohort (10/17, 59%), and in resected stage I lung cancer (29/63, 46%)." (PMID 33096780, 2020). "A previous study showed that the ADAM9-CDCP1 signaling pathway plays a role in the progression of lung cancer and ADAM9 enhances CDCP1 expression in lung cancer cell lines." (PMID 33260155, 2020). "Taken together, these results suggest that ADAM9 participates in tumor angiogenesis by increasing the activity of various angiogenic proteins in lung cancer." (PMID 33096780, 2020). "At present, it is known that, compared with human lung cancer squamous carcinoma cell lines that have tropism migration to bone tissue, the mRNA and protein expression levels of ADAM9 are significantly enhanced in strains that have tropism to brain tissue." (PMID 32875951, 2020). "Other studies indicated that circRNA_0020123 participates in the development of lung cancer by interfering with the miR-488-3p/ADAM9 axis." (PMID 32508871, 2020). "Studies on HCC cells and lung cancer cells showed that ADAM9, triggered by IL-6 which activates the JNK signaling pathway, induces the expression of the EMT-associated transcription factor SNAIL through NOX1 expression in the cell membrane and ROS production." (PMID 31641356, 2019). "(2017) evaluated the critical role of ADAM9 in lung cancer metastatic process and angiogenesis in vivo." (PMID 30556643, 2019).
lung carcinoma (continued). "In lung cancer metastasis, ADAM9 increases the expression of VEGF A, ANGPT2, and PLAT and activates EGFR." (PMID 31641356, 2019). "More importantly, ADAM9 and ADAM10 expression have also been reported to be associated with various human cancers, including pancreatic cancer and lung cancer." (PMID 29416721, 2018). "miRNA-1 expression was shown to be down-regulated in primary lung tumors but increased in ADAM9-knockdown lung cancer cells." (PMID 29868480, 2018). "Our results showed ADAM9 silence in lung cancer cells significantly reduce the VEGFA and ANGPT2 expression." (PMID 29118335, 2017). "miR-1 expression was down-regulated in lung tumors, but increased in ADAM9-knockdown lung cancer cells, and was negatively correlated with CDCP1 expression as well as the migration ability of lung cancer cells." (PMID 28537886, 2017). "The observation in animal models is consistent with the clinical dataset analyses that poor outcomes in lung cancer patients with simultaneous high expression of ADAM9 and VEGFA or of ADAM9 and ANGPT2." (PMID 29118335, 2017). "We believe that ADAM9 inhibitions in protein expression and protease activity are potential therapeutic approaches for treatment of lung cancer." (PMID 29118335, 2017). "In our study, a higher concentration of VEGFA was detected in ADAM9-abundant lung cancer cells compared to ADAM9 knockdown cells and resulted in higher angiogenesis in endothelial tube formation assays." (PMID 29118335, 2017). "In our previous study, we found that ADAM9 enhanced lung cancer migration by up-regulating CDCP1 and that blocking the two proteins reduced lung cancer metastasis." (PMID 28537886, 2017). "ADAM9 promotes lung cancer metastasis through increase of CDCP1 expression and activation of CDCP1 function." (PMID 28537886, 2017). "Up-regulation of a disintegrin and metalloproteinase 9 (ADAM9) in lung cancer cells is correlated with metastasis to the brain." (PMID 29118335, 2017). "We show that ADAM9 promotes vascular remodeling in lung cancer cells by increasing the expression of VEGFA, ANGPT2, and PLAT." (PMID 29118335, 2017). "A disintegrin and metalloprotease 9 (ADAM9) and CUB-domain-containing protein 1 (CDCP1) are both oncogenic membrane proteins associated with lung cancer metastasis." (PMID 28537886, 2017). "In this study, we demonstrate that VEGFA, ANGPT2, and PLAT are up-regulated in ADAM9-expressing lung cancer cells." (PMID 29118335, 2017). "Ectopic overexpression of ADAM9 in lung cancer cells results in cancer cells metastasizing to the brain in animal models." (PMID 29118335, 2017). "Taken together, these results demonstrate that miR-1 expression is inhibited in lung cancer cells and can be restored in lung cancer cells by ADAM9 knockdown." (PMID 28537886, 2017). "ADAM9 regulates lung cancer metastasis to the brain by facilitating the tPA-mediated cleavage of CDCP1." (PMID 27018053, 2016). "Our previous study demonstrated that ADAM9 promotes lung cancer metastasis by enhancing the function of CDCP115." (PMID 26553452, 2015). "Previously, we found that ADAM9-depleted lung cancer cells decreased CDCP1 expression and cell migration." (PMID 26553452, 2015). "In the current study, we aimed to better understand the relationship between CDH2 and ADAM9 in lung cancer brain metastasis." (PMID 24705471, 2014). "Because microRNAs regulate many biological functions and disease processes (e.g., cancer) by down-regulating their target genes, microRNA microarrays were used to identify ADAM9-regulated miRNAs that target CDH2 in aggressive lung cancer cells." (PMID 24705471, 2014). "Over-expression of ADAM9 in lung cancer cell lines resulted in enhanced invasiveness and was significantly associated with brain metastases." (PMID 18582378, 2008). "In turn, in lung cancer, ADAM9 increases angiogenesis and enhances pulmonary vascular remodeling." (PMID 36522710, 2022). "In lung cancer, the dysregulation of ADAM9 was documented long ago." (PMID 33096780, 2020).
lung carcinoma (continued). "In lung cancer, the dysregulation of ADAM9 expression has been documented long ago." (PMID 32875951, 2020). "Thus, ADAM9 promotes the CDCP1 activation for lung cancer metastases to the brain through a tPA-based pathway." (PMID 33096780, 2020). "The ADAM9-CDCP1 axis was confirmed to be necessary for lung cancer cell migration and survival in vitro and in vivo; and moreover, the authors demonstrated that ADAM9 decreases the expression of miR-1 and miR-218, which target the 3′-UTR of CDCP1 to suppress its expression." (PMID 33096780, 2020). "ADAM9 (A Disintegrin and Metalloproteinase 9) is a cell-surface membrane glycoprotein that is overexpressed in a number of cancers, including gastric cancer, lung cancer, breast cancer, prostate cancer, and liver cancer." (PMID 33260155, 2020). "Various studies demonstrate that ADAM9 is a major player in lung cancer progression and metastasis." (PMID 33096780, 2020). "In lung cancer cells, ADAM9 expression contributes to a pro‐angiogenic expression signature." (PMID 30556643, 2019). "Overexpression of ADAM9 in lung cancer cells is correlated with brain metastasis." (PMID 28537886, 2017). "Because the miRNA profile typically changes in lung cancer, it is important to determine whether oncogenic proteins, such as ADAM9, contribute to manipulating several critical miRNAs in cancer progression." (PMID 28537886, 2017). "Finally, we demonstrated that simultaneous high expression of ADAM9/VEGFA or ADAM9/ANGPT2 are linked to poor prognosis, which shows the clinical relevance of ADAM9-mediated vascular remodeling in lung cancer progression." (PMID 29118335, 2017). "However, CDCP1 levels and EGFR signaling, as indicated by phospho-EGFR expression, were dampened in ADAM9-knockdown lung cancer cells, and ADAM9-knockdown cells showed more sensitivity to EGFR inhibitor treatment (Tarceva) than control cells (shGFP)." (PMID 28537886, 2017). "Our previous study demonstrated that ADAM9 promotes lung cancer metastasis by enhancing the function of CDCP1 and regulates the expression of several genes through dysregulation of miRNAs, such as activation of N-cadherin (CDH2; cadherin 2) and CDCP1 through miR-218." (PMID 28537886, 2017). "By linking the function of ADAM9 to clinically relevant outcomes in lung cancer patients, we have demonstrated that ADAM9 could be useful as both a prognostic biomarker and as a molecular target for reducing cancer progression." (PMID 29118335, 2017). "Taken together, these results show that miR-218 expression is decreased in lung cancer cells and could be re-induced in ADAM9 knockdown lung cancer cells." (PMID 26553452, 2015). "Ectopic expression of ADAM9 in lung cancer cells is correlated with brain metastasis." (PMID 26553452, 2015). "Adding sub-groups stratified by ADAM9 expression into the lung cancer TNM stage system may also help to supply more accurate information for assessing prognosis." (PMID 23761811, 2013). "Several studies have found that ADAM9 is overexpressed in solid tumors, including gastric cancer (GC), prostate cancer (PCa), liver cancer, melanoma, pancreatic ductal adenocarcinoma, breast cancer (BC), glioma, and lung cancer, providing a new target for the treatment of tumors." (PMID 34528498, 2021). "Also, silencing ADAM9 or CDCP1 in lung cancer Bm7 cells decreased their migration." (PMID 26553452, 2015). "However, the expression of ADAM9 in human resected lung cancer tissue and its clinical significance remain unclear." (PMID 23761811, 2013). "In a subsequent study, they proposed that ADAM9 inhibits miR-1 through activation of epidermal growth factor receptor, thereby enhancing the role of CDCP1 in lung cancer metastasis." (PMID 39441449, 2024). "We found that ADAM9 also down-regulated several other miRNAs, such as miR-766 and miR-612, that target CDCP1 in lung cancer cells." (PMID 28537886, 2017).
lung carcinoma (continued). "In summary, we found that ADAM9 controls CDCP1 function by increasing its expression and activity, which results in lung cancer metastases." (PMID 28537886, 2017). "Inhibition of ADAM9 protein expression or protease activity rescued miR-1 suppression and down-regulated expression of its target CDCP1 in lung cancer cells." (PMID 28537886, 2017). "To further investigate the role of ADAM9 in vivo, we knocked out ADAM9 in TC1 mouse lung cancer cells using a CRISPR/Cas9 system." (PMID 29118335, 2017). "In a subsequent study, it was shown that ADAM9 regulated miR-218, which targets CDH2 in aggressive lung cancer cells." (PMID 27018053, 2016). "Currently, several genes related to lung cancer brain metastases have been identified, such as CDH2 and ADAM9." (PMID 24705471, 2014). "However, the ADAM9/CDCP1/t-PA pathway and their aberrant expressions have so far been human lung adenocarcinoma cell lines and lung cancer." (PMID 39441449, 2024). "Compared with the matched non-tumorous tissues, lung cancer tissues exhibited higher expression levels of ADAM9 mRNA." (PMID 36171576, 2022). "In addition to ADAM9, ADAM10 and ADAM17 are also known to predict poor prognosis in hepatocellular carcinoma and lung cancer, based on previous studies." (PMID 35740916, 2022). "Moreover, in vitro and in vivo results demonstrated that REMAIN effectively induced apoptosis of lung cancer cells and inhibited LUAD development and progression by targeting ADAM9." (PMID 36171576, 2022). "One study revealed the snail-independent transcription of ADAM9 in lung cancer cell lines, without showing the exact mechanism." (PMID 32210761, 2020). "ADAM9 and CDCP1 were reported to show increased expression in cells with progressive migration ability (CL1-0 < F4 < Bm7brm) from the same original tumor; we found that miR-1 expression was lower in the lung cancer cells with greater migration." (PMID 28537886, 2017). "Thus, the results indicated that ADAM9 can reduce miR-1 levels and increase CDCP1 expression in lung cancer cells." (PMID 28537886, 2017). "Moreover, we also measured the expression of ADAM9 mRNA in 67 freshly collected lung cancer tissues and adjacent non-tumorous tissues." (PMID 36171576, 2022). "The cell lines exhibiting the strongest co-expression of ADAM9, TNFRSF12A, and AXL were 2 ovarian cancer lines (OVCAR_8 and SK_OV_3), lung cancer line HOP_92, and several renal cancer lines, suggesting that these cell lines may be particularly active in degrading extracellular matrix." (PMID 22570691, 2012). "Using IPA’s Biomarker Filter (Homo sapiens; cancer; lung cancer cell lines), three genes in our panel mapped to established biomarkers (not specifically for MMP12 inhibition): ADAM9 (efficacy/prognosis), CD44 (diagnosis/progression/prognosis), and MMP12 (efficacy)." (PMID 41465234, 2025). "However, the functional difference between the 180-kDa and 120-kDa fragments of Col XVII remained unclear, and the involvement of ADAM9 and ADAM10 in Col XVII shedding and in inducing EMT phenotypes in lung cancer has not been reported." (PMID 29416721, 2018). "VEGFA and ANGPT2 are the targets of anti-angiogenesis therapy, and whether the combined inhibition of ADAM9 with bispecific antibody (A2V CrossMab) against both Ang-2 and VEGF can reduce the morbidity and mortality of lung cancer brain metastasis has not been studied." (PMID 35874764, 2022).